KRT17 (keratin 17)
Diseases named in the same sentence as KRT17 in open-access papers (continued):
Sharing a sentence is not in itself a finding about the gene and the disease.
pulmonary fibrosis (16 papers, 2020 to 2025). Chronic progressive interstitial lung disorder characterized by the replacement of the lung tissue by connective tissue, leading to progressive dyspnea, respiratory failure, or right heart failure. "Our findings suggest KRT17+KRT5– cells represent a convergent pathogenic mechanism in lung fibrosis, making them attractive therapeutic targets for CLAD, where treatment options remain severely limited." (PMID 41122970, 2025). "Previous studies have shown that Pla2g10 expression increases in ciliated cells and KRT5−/KRT17+ cells but decreases in AT2 cells in a bleomycin-induced pulmonary fibrosis mouse model, with symptoms improving after intervention." (PMID 40278587, 2025). "Loss of Sox2 promotes KRT17+KRT5– dysplastic epithelium after injury in the distal lung that is present in IPF lungs and patients with post-COVID-19 pulmonary fibrosis." (PMID 39927460, 2025). "COVID-19 patients with pulmonary fibrosis show an accumulation of KRT17+ epithelial cells, which express high levels of TGF-beta." (PMID 37511258, 2023). "These cells were first identified in single-cell studies as KRT17+/KRT5- basaloid cells in human idiopathic pulmonary fibrosis (IPF) lungs and independently shown by in vitro studies to arise from AT2 cells." (PMID 37830426, 2023). "Single cell analysis of human lung fibrosis recently identified a disease specific cell state that was termed aberrant basaloid cell (KRT17+/KRT5-) based on some similarities to airway basal cells." (PMID 32678092, 2020). "Among the top upregulated DEGs, notable markers included MMP7, a metalloproteinase involved in extracellular matrix (ECM) degradation and biomarker of pulmonary fibrosis; KRT17, an epithelial basal cell marker overexpressed in idiopathic pulmonary fibrosis; and SPP1, a biomarker of IPF." (PMID 38348044, 2024). "If validated, the identification of KRT17+KRT5− basaloid cells or profibrotic alveolar macrophages in bronchoscopic biopsies may assist in identifying patients with irreversible lung fibrosis in the future." (PMID 33257409, 2020). "In addition, KRT17 has emerged in other disease contexts as well, such as in idiopathic pulmonary fibrosis, where a distinct population of aberrant basaloid cells—likely derived from alveolar type II cells—ectopically express KRT17, indicating a pathological epithelial reprogramming." (PMID 41479908, 2025). "scRNA-seq analysis identified two ABC subsets: Krt5low Tp63low Krt17+ ABCs_1, found in patients with idiopathic pulmonary fibrosis (IPF), and Krt5hi Tp63hi Krt17+ ABCs_2, which have been observed in cultured tissues from patients with IPF but not in traditional murine models." (PMID 41168897, 2025). "Recent studies using a high-resolution scRNA-seq analysis reported that a transcriptionally distinct KRT17+ population accumulates aberrantly in a non-permissive pathologic environment, such as with idiopathic pulmonary fibrosis (IPF)." (PMID 32750316, 2020). "Direct comparison of differential gene expression in basal cells (cluster 1) or KRT17+KRT5− cells (cluster 7) in lung tissue from patients with COVID-19 or patients with pulmonary fibrosis did not identify genes uniquely present in one condition, highlighting similarities between these two diseases." (PMID 33257409, 2020).
bladder cancer (15 papers, 2011 to 2025). "Exploration of Keratin 17 as a biomarker associated with bladder cancer has been recently investigated." (PMID 38751950, 2024). "Preliminary evidence indicates that Keratin 17 expression may hold diagnostic value beyond bladder cancer, extending to upper tract urothelial carcinoma (UTUC)." (PMID 41303144, 2025). "Urinary EV SLC2A1, GPRC5A and KRT17 were overexpressed in pT1 and higher stage bladder cancer by 20.6-fold, 18.2-fold and 29.5-fold, respectively." (PMID 30214686, 2018). "KRT17 has been described previously as expressed in urothelium and as activated through hypomethylation at the promotor in bladder cancer and here we show a distinct localization to the intermediate/ basal cells." (PMID 26694548, 2015). "These accumulating data support the validity of KRT17 as a marker for bladder cancer." (PMID 38514751, 2024). "However, there are few reports on the epigenetic regulation and expression of keratin 17 in bladder cancer." (PMID 22140553, 2011). "KRT17 expression was significantly high in pT1 (11.5-fold, p = 2.7 x 10-7), pT2 and higher stages (15.0-fold, p = 4.0 x 10-4), G2 (1.4-fold, p = 0.022) and G3 bladder cancer (6.7-fold, p = 1.8 x 10-6), which was consistent with the expression of SLC2A1 and GPRC5A." (PMID 30214686, 2018). "This study evaluates the efficacy of Acu‐URO17, a highly sensitive and specific immunocytochemistry (ICC) test targeting Keratin 17, in comparison to urine cytology and UroVysionTM fluorescence in situ hybridization (FISH) for detecting bladder cancer cells in voided urine specimens." (PMID 38751950, 2024). "In this study, we identified an increase of KRT17 expression in bladder cancer tissues compared with their normal counterparts." (PMID 22140553, 2011).
melanoma (15 papers, 2012 to 2024). A malignant, usually aggressive tumor composed of atypical, neoplastic melanocytes. "A recent study found that a higher expression of KRT1 and KRT17 is associated with low overall survival in melanoma." (PMID 38791062, 2024). "Particularly, the melanoma type specific mutated gene KRT17 encodes the keratin 17 which belongs to a group of fibrous proteins forming the structural framework of certain cells, particularly for the skin." (PMID 22691569, 2012). "Increased expression of KRT6B, KRT14, and KRT17 was associated with poor survival in melanoma." (PMID 36553569, 2022). "LogFC values and expression patterns of KRT17 closely follow those of KRT16 in all seven melanoma cell lines." (PMID 36139698, 2022). "In the current study, we found that KRT17 significantly overexpressed in primary melanoma than metastatic melanoma, and their expression levels were markedly correlated with the tumor stage of the SKCM patients." (PMID 33441834, 2021). "All genes except the two keratin genes (KRT6B and KRT17) were up-regulated in cutaneous melanoma compared to primary melanoma." (PMID 31199813, 2019). "Interestingly, the high KRT17 expression was significantly but inversely, correlated with poor OS in melanoma patients." (PMID 33441834, 2021). "In addition, the expression of KRT17 was low in glioma, LIHC, renal cancer, testicular cancer, and melanoma tissues, but significant differences were still observed between tumor and normal tissues." (PMID 35646078, 2022). "In glioma, liver cancer, kidney cancer, testicular cancer, and melanoma, KRT17 expression is low but higher than that in corresponding normal tissues." (PMID 35646078, 2022). "In addition, KRT17 and KRT15 were up-regulated and demethylated in the eIF6-high expressed melanoma, suggesting that DNA demethylation was a potential transcription regulation mechanism of eIF6." (PMID 35707354, 2022). "Genes, such as members of the keratin family (KRT17, KRTDAP, KRT6B, KRT14, KRTAP13-2) are expressed more in primary tumor, possibly indicating the differentiated status of less advanced cancers, or this could be a disruption in their normal expression by melanoma processes." (PMID 36553569, 2022).
pachyonychia congenita (15 papers, 2012 to 2025). Pachyonychia congenita (PC) is a rare genodermatosis predominantly featuring painful palmoplantar keratoderma, thickened nails, cysts and whitish oral mucosa. "A heterozygous KRT17 mutation (c.373C > A; p.Pro125Thr) confounded the diagnosis, exhibiting overlap with pachyonychia congenita but devoid of mucosal manifestations, aligning with broader keratin-associated symptoms." (PMID 41393054, 2025). "Mutations in KRT6B and KRT17 are responsible for pachyonychia congenita." (PMID 30061793, 2018). "Autosomal dominant pachyonychia congenita (PC) has been linked to pathogenic variants of KRT17." (PMID 41393054, 2025). "In clinical contexts, specific KRTs, including KRT17 and KRT6A, are associated with keratinization disorders such as epidermolytic hyperkeratosis, ichthyosis, and pachyonychia congenita." (PMID 39201815, 2024). "Pachyonychia congenita (PC) is a rare hereditary condition affecting keratinization, which results from an underlying genetic mutation in one of the five keratin genes: KRT6A, KRT6B, KRT6C, KRT16, or KRT17." (PMID 40686559, 2025).
lung carcinoma (13 papers, 2016 to 2025). "KRT17 is highly expressed in lung cancer tissues, and the high expression of KRT17 is associated with the histological type (p < 0.001), degree of differentiation (p = 0.011), sex (p < 0.001), age (p = 0.024), and lymph node metastasis (p = 0.04)." (PMID 35281081, 2022). "It was also proven to facilitate lung cancer cell proliferation and invasion, and elevated KRT17 is closely related to a poor prognosis." (PMID 36428672, 2022). "Circular RNA KRT17 (circKRT17) is elevated in osimertinib-resistant lung cancer cells by a circRNA microarray analysis." (PMID 36428672, 2022). "They discovered that KRT17 greatly reduced the capacity of lung cancer cells to spread." (PMID 36765563, 2023). "However, only 239 patients were included in the two studies, so a larger sample size is needed to confirm the role of KRT17 in survival outcomes in patients with different types of lung cancer." (PMID 35646078, 2022). "Prognostic associations of KRT5 and KRT14 have been implicated in lung cancer, while the relationship and molecular mechanisms of KRT6A and KRT17 in the lung cancer are still unknown and should be further elucidated." (PMID 27684953, 2016). "However, the overexpression of KRT17 in lung cancer cells showed the opposite result." (PMID 35281081, 2022). "However, KRT17 has different characteristics in different pathological types of lung cancer, and we need to further study the expression and mechanism of KRT17 in different pathological types, so as to provide a strong basis for the treatment and prognosis of lung cancer." (PMID 35281081, 2022). "Therefore, KRT17 may be a potential therapeutic target and prognostic marker for lung cancer." (PMID 35281081, 2022). "CircKRT17 (hsa_circ_0043632), a circRNA that is derived from the Keratin 17 (KRT17) gene, is elevated in osimertinib-resistant lung cancer cells by a circRNA microarray analysis." (PMID 36428672, 2022).
colorectal cancer (10 papers, 2020 to 2026). A primary or metastatic malignant neoplasm that affects the colon or rectum. "In colorectal cancer, KRT17 has been linked to better clinical outcomes and increased T-lymphocyte infiltration, potentially reversing immune escape mechanisms." (PMID 41550766, 2026). "In colorectal cancer, KRT17 is highly expressed in cancer tissues, and this high expression is negatively correlated with disease-free survival." (PMID 35281081, 2022). "KRT17 knockout decreases both protein and mRNA in colorectal cancer cells and inhibits the proliferation and invasion of colorectal cancer cells." (PMID 35281081, 2022). "Studies have also shown that KRT17 is negatively expressed in normal colorectal mucous and highly expressed in colorectal cancer." (PMID 35281081, 2022). "Moreover, KRT17 expression was proposed as a prognostic marker that can discriminate postoperative stage II patients with colorectal cancer with a high probability of disease recurrence, as support to available risk stratification factors." (PMID 32560331, 2020). "In addition, KRT17 is highly expressed in colorectal cancer cells." (PMID 35281081, 2022). "We found that KRT17 was overexpressed in BRCA, CESC, and colorectal cancer tissues versus normal tissues, and the difference was statistically significant." (PMID 35646078, 2022).
breast tumors (8 papers, 2008 to 2021). "They indicated that most responsive breast tumors had the highest expression of Keratin 5/7 (KRT5/KRT17) and the lowest expression of endogen receptor (ER), progesterone receptor (PR) or human epidermal growth factor receptor-2 (HER2)." (PMID 28446239, 2017). "Several overlapping genes especially the ones present in all datasets (ESR1, FOXA1, KRT17) are known to play critical roles in the subtyping and carcinogenesis of breast tumors." (PMID 26404658, 2015). "Forty-eight (94%) triple-negative breast tumors and 18 (17%) luminal breast tumors were clustered together, showing prominent basal-like characteristics where basal marker genes KRT5 and KRT17 were markedly up-regulated." (PMID 23049873, 2012). "In their hierarchical clustering analyses, basal-like breast tumors were grouped together within a tight cluster showing high expression of basal cytokeratin genes (KRT5 and KRT17) and low expression of luminal estrogen receptor gene (ESR1)." (PMID 23049873, 2012).
colon cancer (8 papers, 2018 to 2024). "Although, it has been reported that the expression of KRT17 in colon cancer tissues was higher than that in normal colonic epithelial tissues, and increased concomitantly with the grade of T staging progresses." (PMID 34935584, 2021). "Cell- and animal-based experiments showed that overexpression of KRT17 promoted the invasion and metastasis of colon cancer cells while knocking down KRT17 reversed these processes both in vitro and in vivo." (PMID 34935584, 2021). "In summary, these findings suggested that high expression of KRT17 could promote cell metastasis and angiogenesis of colon cancer cells by regulating the WNT/β-catenin signaling pathway." (PMID 34935584, 2021). "Taken together, our data suggested that KRT17 could promote migration and invasion of colon cancer cells both in vitro and in vivo." (PMID 34935584, 2021). "However, the role of KRT17 in the biological behavior of colon cancer cells and related molecular mechanisms remain unclear." (PMID 34935584, 2021). "Several studies have shown that the expression of keratins, such as KRT17 and KRT15, is higher in colon cancer tissues than in normal colonic epithelial tissues, and increased concomitantly as the grade of T staging progresses." (PMID 36217128, 2022). "To understand how KRT17 affected the progression of COAD, we performed several experiments in vivo and in vitro and found that increased expression of KRT17 could promote the invasion and migration of colon cancer cells." (PMID 34935584, 2021).
head and neck squamous cell carcinoma (8 papers, 2007 to 2024). A squamous cell carcinoma that arises from any of the following anatomic sites: lip and oral cavity, nasal cavity, paranasal sinuses, pharynx, larynx, and salivary glands. "One cluster included Keratin 14, 17 and LY6D; Keratin 17 is a known human basal-like tumor marker, while LY6D is a member of the Ly6 family of glycosylphosphatidylinositol (GPI)-anchored proteins that is highly expressed in head and neck squamous cell carcinomas." (PMID 17493263, 2007).
idiopathic pulmonary fibrosis (8 papers, 2020 to 2025). Idiopathic pulmonary fibrosis (IPF) is a nonneoplastic pulmonary disease that is characterized by the formation of scar tissue within the lungs in the absence of any known cause. "An analogous population of Krt17+Krt5− aberrant basaloid cells has been described in idiopathic pulmonary fibrosis (IPF), which co-express several basal epithelial, mesenchymal and senescence markers." (PMID 38077031, 2023).
cervical squamous cell carcinoma (7 papers, 2021 to 2024). A squamous cell carcinoma arising from the cervical epithelium. "Accumulated evidence suggests that KRT17 is also abnormally expressed in cervical squamous cell carcinoma and gastric cancer." (PMID 38434984, 2024). "The further IHC results suggested that KRT17 was dominantly expressed in the cervical squamous cancer and barely expressed in the normal cervix; while CRISP2 was specifically lowly expressed in HSIL." (PMID 33624385, 2021). "Combined analysis of KRT17, CRISP2 expression at both genetic and protein levels can determine different histological grades of cervical squamous cell carcinoma." (PMID 33624385, 2021). "However, there are challenges in identifying specific markers for cervical squamous cell carcinoma (CCSC), including ABCG2, MSI1, PROM1 (CD133), ITGA6 (CD49f), KRT17 (CK17), SOX2, and Pou5f1 (OCT4)." (PMID 38651153, 2024).
epithelial dysplasia (7 papers, 2017 to 2024). "Gain of keratin 17 expression and loss of keratin 13 were significantly observed in differentiated epithelial dysplasia." (PMID 38891785, 2024). "Recent studies investigated the use of keratin 13 (CK13) and keratin 17 (CK17) as indicative markers associated with usual/classic and differentiated epithelial dysplasia, in that dysplastic lesions show a decreased expression of CK13 and an increased expression of CK17." (PMID 31896811, 2020).
esophageal cancer (7 papers, 2022 to 2024). A primary or metastatic malignant neoplasm involving the esophagus. "KRT17 can promote the proliferation and migration of esophageal cancer cells by inducing epithelial–mesenchymal transition (EMT) and activating the Akt pathway." (PMID 35281081, 2022). "Although KRT17 promotes the metastasis of esophageal cancer through the Akt/EMT signaling pathway, this mechanism may not be the only signaling pathway, and there may be other mechanisms, which still need to be further studied." (PMID 35281081, 2022). "KRT17 and COL1A1 are potential biomarkers for esophageal cancer in the Chinese population." (PMID 38979664, 2024). "Core genes KRT17 and COL1A1 were used to test the efficacy of esophageal cancer." (PMID 38979664, 2024).
head and neck cancer (7 papers, 2020 to 2025). A primary or metastatic malignant neoplasm affecting the head and neck. "KRT17 is involved in immune evasion and resistance and is part of a multiomic signature predicting survival in head and neck cancer." (PMID 40014866, 2025). "Our pilot data suggest the expression of cytokeratin 17 in pretreatment tumor samples predicts response to ICB in head and neck cancer." (PMID 37835599, 2023). "Our study revealed cytokeratin 17 may be an independent predictive biomarker of inferior response to ICB in head and neck cancer." (PMID 37835599, 2023).
ovarian carcinoma (7 papers, 2008 to 2025). A malignant neoplasm originating from the surface ovarian epithelium. "The results confirm that the high expression of KRT17 is significantly associated with tumour progression and poor prognosis in ovarian cancer." (PMID 35281081, 2022). "KRT17 is a marker of cervical and ovarian cancer, and PGR plays a role in estrogen and progesterone signaling." (PMID 36389068, 2022). "Multivariate analysis showed that the high expression level of KRT17 was an independent prognostic factor for OS in ovarian cancer patients." (PMID 35281081, 2022). "KRT17’s involvement in cellular stress response by the activation of downstream signaling, including the PI3K/Akt pathway, has previously been reported in ovarian cancer models." (PMID 41399494, 2025). "Both mRNA and protein expression levels of KRT17 were significantly higher in ovarian cancer tissues than in non-cancerous tissues." (PMID 35281081, 2022).